MIR548P (microRNA 548p)
Synonyms: hsa-mir-548p; MIRN548P
Gene: MicroRNA gene on chromosome 5 (100,816,482 to 100,816,565, reverse strand). Ensembl gene ENSG00000221263.
Homologues: Orthologues: chimpanzee ptr-mir-548p (100% identical). Paralogues in human: MIR548F1 (82% identical), MIR548F3 (81% identical), MIR548AZ (80% identical), MIR548H3 (79% identical), MIR548X (75% identical), MIR548K (74% identical), MIR548AA1 (73% identical), MIR548AN (73% identical), MIR548N (73% identical), MIR548X2 (73% identical), MIR548S (71% identical), MIR548Z (71% identical), and 13 more.